CD40 (CD40 molecule)
Diseases named in the same sentence as CD40 in open-access papers (continued):
Sharing a sentence is not in itself a finding about the gene and the disease.
diabetes (34 papers, 2010 to 2025). "Blood levels of the CD154 cofactor and expression of CD40 in Müller glia and P2X7R in the retinal endothelial cells and microglia/macrophages are increased in diabetes, increasing the pathogenic effect of the CD40-ATP-P2X7R axis in these patients." (PMID 34281162, 2021). "Lower levels of CD40 on DCs were associated with higher numbers of Tregs and inhibition of diabetes in an infection-driven model of type 1 diabetes." (PMID 26124756, 2015). "Upon observing the enhanced activation of P14 T cells in response to antigen in the presence of anti-CD40 we questioned whether the cells were now capable of infiltrating the pancreas and causing diabetes." (PMID 28257518, 2017). "Altogether, these results support that AGEs promote CD40 upregulation in the setting of diabetes and potentiate the inflammatory effects of CD40." (PMID 38474393, 2024). "Previous studies demonstrated a critical role for CD40 in the pathogenesis of diabetes-induced retinal inflammation." (PMID 37958563, 2023). "Among the diabetes-associated mechanisms studied, only TNF-α induced significant upregulation of membrane-bound CD40 expression on Müller cells and HRMECs." (PMID 37958563, 2023). "Other studies also suggest the implication of the CD40/CD154 pathway; CD154 increase is detected in diabetes and CD40 upregulation is observed in retinal endothelial cells, Müller cells and microglia from diabetic mice, mediating vascular retinal damage." (PMID 36869375, 2023). "Researchers have also discovered that IL-17A is a characteristic proinflammatory cytokine in the serum and urine of patients with diabetes, and CD40 expression was observed to be increased in podocytes with DN." (PMID 36776877, 2023). "For example, the ligand for CD40 and expression of MCP1 are upregulated in the acute phase of atherothrombotic stroke, which is also associated with vascular events with diabetes." (PMID 38156087, 2023). "In the diabetic retina, CD40 and P2X7 upregulate a broad range of inflammatory molecules that promote development of diabetic retinopathy." (PMID 35920844, 2022). "By culturing HUVECs with high-glucose medium as a model mimicking microangiopathy in uncontrolled hyperglycemia of diabetes, we demonstrated, for the first time, that CD40 was induced by high-glucose exposure." (PMID 29549140, 2018). "In NOD mice that develop spontaneous diabetes, substantial thymic increases in numbers of CD40+ thymocytes were observed." (PMID 28878738, 2017). "It remains to be determined how CD40 is upregulated in diabetes and how CD154 gains access to the retina." (PMID 31740645, 2017). "CD28 and CD40 have disparate effects on inducing these T cell fates in NOD mice, as a loss of CD28 can restore diabetes in CD40L-deficient mice and alters the number of Tregs in those mice." (PMID 26124756, 2015). "Previous experiments with adoptive transfers of mature bone-marrow derived DCs expressing high levels of co-stimulatory molecules, such as CD80, CD86 and CD40, significantly reduced diabetes incidence in NOD mice." (PMID 25166904, 2014). "CD40, a co-stimulatory protein, is critical in B-cell activation and autoantibody production, contributing to glandular inflammation in Sjögren’s syndrome and immune dysregulation in diabetes and celiac disease." (PMID 40839671, 2025). "In the present study, we investigated the effect of various diabetes-associated mechanisms such as high-glucose, the hypoxia mimetic agent CoCl2, VEGF and the proinflammatory cytokine TNF-α on the expression of membrane-bound CD40 and sCD40." (PMID 37958563, 2023). "Moreover, in the presence of diabetes, B6 mice and Trg-CD40 WT mice upregulate P2x7 mRNA levels, consistent with the notion that P2X7 upregulation accompanies and facilitates in vivo purinergic signalling." (PMID 35920844, 2022). "Indeed, CD40 mRNA is upregulated in the retina of mice with diabetes and mice subjected to retinal I/R." (PMID 31921199, 2019).
diabetes (continued). "In summary, this study demonstrated that microangiopathy, including morphological and molecular alterations, is a major pathology substrate of diabetic nerve degeneration, and provides evidence that the CD40 signaling pathway mediates the interactions between inflammation and thrombosis in diabetes." (PMID 29549140, 2018). "Firstly, activated platelets could express soluble CD40 ligand (CD40L) and CD40L and its receptor CD40 extensively involved in oxidative stress and inflammatory pathways, which may play a role in the development of diabetes." (PMID 29651306, 2018). "Given that primary human pericytes also express CD40 (J-A Portillo and C.S. Subauste, unpublished observations), it is possible that the CD40-ATP-P2X7 pathway may also mediate PCD of retinal pericytes in diabetes." (PMID 31740645, 2017). "Altogether, the CD40-ATP-P2X7 pathway appears to be an important driver of PCD of REC in diabetes." (PMID 31740645, 2017). "Notably, the anti-CD40 agonistic antibody was superior at inducing diabetes, followed by CpG and LPS." (PMID 24647761, 2014). "The SNP rs1883832 maps in the functional region of the CD40 gene, i.e. the kozak consensus sequence and has recently been associated with ACS risk independent of the traditional risk factors such as hypertension and diabetes mellitus." (PMID 24828072, 2014). "In addition, the proteomic and genomic analysis in plasma and vascular bypass tissue of CHD patients without comorbidities or with the comorbidities hypertension and/or hypertension + diabetes identified some key mediators of CD40(L)–TRAF signaling, centered around TNFα." (PMID 38554187, 2024). "Indeed, studies involving transgenic mice showed that after the induction of diabetes, the expression of CD40 restricted to endothelial or Müller cells was sufficient to induce inflammatory responses in the retina and, in the case of Müller cells, promote the development of diabetic retinopathy." (PMID 38474393, 2024). "In addition to VEGF-A, we found multiple EV inflammatory proteins that may give further insight on the pathophysiology of diabetes, including cluster of differentiation 40 (CD40)." (PMID 32517700, 2020). "The upregulation of CD40 in endothelial cells, macrophages and T cells in diabetes suggested that enhanced CD40 expression could play a key role in mediating leukocyte adhesion through the CD40-CD40L signaling pathway, resulting in the induction of pro-inflammatory and pro-thrombotic processes." (PMID 29549140, 2018). "Therefore, galectin-9 control of CD40 signals in CD4loCD40+ T cells could be one mode of action for galectin-9 to be protective against diabetes as was demonstrated." (PMID 22685601, 2012). "Thus, the link between AGEs and CD40 may be relevant to various complications of diabetes." (PMID 38474393, 2024). "Thus, CD40 content in EVs may help to predict vascular disease for diabetes mellitus." (PMID 32517700, 2020). "Added to culture of bmDC derived from diabetes-prone NOD mice, EV from cytokine-treated beta cells up-regulate moderately the surface expression of MHC class II and co-stimulatory CD40 molecules." (PMID 33101266, 2020). "The progression to diabetes in control NOD mice was characterized by significantly elevated levels of most Teff subsets (IFN-γ+, Th17+, IL-2+, TNF-α+ and CD40+ lymphocytes) in the pancreatic lymph node." (PMID 26674203, 2015). "Recently, CD40/CD40L pathway activation and a subsequent proinflamatory milieu were reported in diseases such as obesity, diabetes mellitus and hypertension." (PMID 21331754, 2011). "Additionally, sciatic nerve samples from Type 2 diabetes mellitus (T2DM) patients show macrophage and T-cell infiltration and increased expression of clusters of cells expressing CD40." (PMID 39075499, 2024).
diabetes (continued). "Finally, the whole heart extracts were examined with a Mouse cytokine array assay of 96 factors, which revealed a decrease in CD40, CTACK, CXCL1, MIP1γ, and sTNFRI, also supporting that glycyrrhizin halts myocardial inflammation in diabetes." (PMID 35281739, 2022). "Replacing WT CD40 with CD40 ΔT2,3 impaired activation of PLCγ1 in Müller cells, upregulation of P2X7 in microglia/macrophages, upregulation of a broad range of inflammatory molecules in the diabetic retina and the development of diabetic retinopathy." (PMID 35920844, 2022). "The upregulation of CD40 and CD154 indicate that this pathway is activated in diabetes." (PMID 31921199, 2019). "CD40 is also expressed by non-immune cells during inflammatory responses including those in diabetes." (PMID 29073149, 2017). "When isolated from diabetic or pre-diabetic NOD mice TH40 cells transfer diabetes readily and without any manipulations; thus CD40 constitutes a diabetogenic T cell biomarker." (PMID 28878738, 2017). "BDC2.5.TCR.Tg mice bred onto the CD40 knockout background did not develop diabetes at any age and equally impressive, those mice did not exhibit insulitis." (PMID 28878738, 2017). "An important discovery was that expansion of the CD4loCD40+ T cell subset and diabetes onset in the non-obese diabetic (NOD) T1D mouse model is prevented by blocking CD40 – CD154 interaction." (PMID 22685601, 2012). "A possible next step could be to label Iscalimab, a human anti-human CD40 monoclonal antibody produced by Novartis, which is currently being tested in SLE, Sjögren’s disease and Type 1 Diabetes Mellitus (Clinical trial # NCT03656562, NCT03905525, NCT04129528)." (PMID 35336782, 2022). "Taken together, these studies suggest that CD40-mediated P2X7 upregulation and hyperglycemia-induced changes in intrinsic receptor properties may contribute to the increased death of retinal capillary cells in diabetes." (PMID 31740645, 2017). "Diabetes in these mice does not develop spontaneously, and it could be induced only by parenteral co-administration of gp33 peptide and a CD40 agonist antibody." (PMID 20625402, 2010). "The current work centered on Müller and endothelial cells because CD40 expressed in non-hematopoietic cells is central to the development of inflammation, and the expression of CD40 restricted to Müller or endothelial cells is sufficient to induce retinal inflammation in the setting of diabetes." (PMID 38474393, 2024). "Importantly, although antigen exposure combined with anti-CD40 or CpG could promote CD8 infiltration into the islets and prolonged IFN-γ production, diabetes was not induced." (PMID 28257518, 2017).
Sepsis (29 papers, 2008 to 2025). Sepsis is defined as life-threatening organ dysfunction caused by a dysregulated host response to infection. "Because the expression of CD40 is also regulated by other posttranslational control mechanisms, such as miRNAs and DNA methylation, further research into the underlying regulatory mechanisms of CD40 in sepsis is also needed." (PMID 29780830, 2018). "In this research, we first performed a case-control study to explore the potential relationship between the CD40 rs1883832 polymorphism and sepsis susceptibility." (PMID 29780830, 2018). "Based on our findings, we conclude that the rs1883832 polymorphism in CD40 gene and the levels of sCD40L were significantly associated with the risk of sepsis in a Chinese population." (PMID 29780830, 2018). "We found that the T allele of CD40 rs1883832 polymorphism was associated with increased risk of sepsis." (PMID 29780830, 2018). "In this study, we explored the association between a functional single-nucleotide polymorphism (SNP) in the CD40 Kozak (rs1883832) sequence and susceptibility to sepsis." (PMID 29780830, 2018). "We found that individuals with the T allele showed higher expression of CD40 at both mRNA and protein levels in sepsis patients." (PMID 29780830, 2018). "When we encounter a sepsis patient with CD40 rs1883832 T allele, it is important to control the sCD40L and other inflammatory parameters into a lower level than C allele carriers to alleviate the sepsis severity." (PMID 29780830, 2018). "This study was designed to investigate the potential association between a functional single-nucleotide polymorphism (SNP) of CD40 (rs1883832) and susceptibility to sepsis." (PMID 29780830, 2018). "Our results suggested that T allele carriers showed significantly higher CD40 expression (both mRNA and protein levels) and sCD40L levels than C allele homozygotes in sepsis patients." (PMID 29780830, 2018). "Our results indicated that the CD40 rs1883832 T allele carriers among sepsis patients exhibited a significant increase in CD40 mRNA expression." (PMID 29780830, 2018). "The results showed that the frequencies of the TT genotype and the CD40 rs1883832 T allele were significantly higher in sepsis patients than in healthy controls." (PMID 29780830, 2018). "We also explored the association of this CD40 polymorphism with CD40 expression in peripheral blood mononuclear cells (PBMCs) from sepsis patients and healthy controls, and the plasma sCD40L concentration was also examined to determine its role in sepsis." (PMID 29780830, 2018). "Furthermore, limited studies have reported the possible association between CD40 gene polymorphisms and sepsis susceptibility, though relevant polymorphisms have been identified to play an essential role in atherosclerosis, ischemic stroke, and Kawasaki disease." (PMID 29780830, 2018). "sPLA2 can enhance the expression of CD86, CD80, CD83, and CD40 on the surface of DCs, promote DC maturation, and improve the prognosis of sepsis (ClinicalTrials.gov ID NCT00034476)." (PMID 38816685, 2024). "Upregulation in sepsis was also detected for co-stimulatory immune checkpoints, such as CD40 on monocytes." (PMID 38187375, 2023). "TRAF6 is a central regulator of sepsis, and blocking CD40–TRAF6 pathway while leaving CD40–TRAF 2, 3, 5 pathways functional would cause less severe immune-suppressive side effects." (PMID 36303116, 2022). "Several genetic variations in genes with immunological functions, such as CTL4, IL1-B, IL6, CD40, and HMGB1, have been reported to be associated with sepsis." (PMID 36714653, 2022). "In fact, it is reported the CD40-/- mice are resistant to LPS-induced lung injury and polymicrobial sepsis." (PMID 35592335, 2022). "According to our findings, CD40 is localized on the membrane of EGCs and overexpressed during sepsis both in CLP model and LPS-induced cell model, following the increased expression of GFAP." (PMID 36303116, 2022).
Sepsis (continued). "It is well established that the activation of the CD40/CD40L pathway is associated with elevated inflammatory cytokines in a wide range of diseases, such as sepsis, ischemic stroke, and hypertension." (PMID 33005203, 2020). "Anti-CD40 treatment provided nearly complete protection against sepsis-induced lymphocyte apoptosis, and improved survival in sepsis." (PMID 32714333, 2020). "The MLN DCs of septic mice exhibited the highest level of CD40 expression, although the expression of CD40 on SP DCs also increased significantly under conditions of sepsis." (PMID 31323786, 2019). "The differences in CD40 expression according to CD40 genotype were analyzed in PBMCs from both sepsis patients and healthy controls." (PMID 29780830, 2018). "But there are also some recent studies that challenge the role of CD40/CD40L in sepsis and inflammatory disorders." (PMID 29780830, 2018). "Differences in sCD40L levels among CD40 genotypes were also further investigated in sepsis patients." (PMID 29780830, 2018). "A further study in sepsis patients showed increased monocyte expression of CD40 compared with healthy control subjects." (PMID 29780830, 2018). "Our data revealed that CD40 expression was significantly higher in sepsis patients compared to healthy controls at both mRNA and protein levels." (PMID 29780830, 2018). "In a lethal polymicrobial sepsis mouse model, CD40 (−/−) mice exhibited significant improvement in mortality, lung injury, and inflammatory cytokine production compared with control mice." (PMID 29780830, 2018). "Inhibition of CD40 by an antagonising antibody inhibits lymphocyte apoptosis and improves survival of murine experimental sepsis." (PMID 18925930, 2008). "Another member of the tumour necrosis factor receptor family, CD40 is expressed on B- and T-lymphocytes during sepsis." (PMID 18925930, 2008). "During sepsis, activated BMVECs express various adhesion molecules, including CD40, e-selectin, VCAM, ICAM, and inflammatory receptors, such as IL-1, TNF-α and TLR4, which facilitate the infiltration of leukocytes and inflammatory mediators into the brain parenchyma." (PMID 36817492, 2023). "Also, anti-CD40 treatment increased the Bcl-x level in splenic B and T cells as well as in thymic T cells, thereby attenuating sepsis." (PMID 36303116, 2022). "In PBMC cultures, zoledronate treatment led to an upregulation of HLA‐DR as well as CD40 and CD64 on sepsis monocytes, which at least in the case of HLA‐DR and CD40 could be inhibited by the addition of neutralising reagents against IFN‐γ and TNF‐α." (PMID 31606902, 2020). "CD40 plays an important role in many inflammatory diseases including sepsis." (PMID 29780830, 2018). "For example, the altered miRNA patterns induced by inflammatory states in sepsis patients may influence CD40 expression at both mRNA and protein levels." (PMID 29780830, 2018). "Therefore, we isolated PBMCs from both sepsis patients and healthy controls to determine CD40 expression levels." (PMID 29780830, 2018). "In conclusion, the CD40 rs1883832 T allele acts as a risk factor for increased susceptibility to sepsis and may be involved in the process of sepsis through regulation of CD40 expression and plasma sCD40L levels." (PMID 29780830, 2018). "All these observations make CD40 an interesting candidate gene for a role in human sepsis." (PMID 29780830, 2018). "In addition, TT genotype carriers among sepsis patients displayed the highest CD40 expression at both the mRNA and protein levels, accompanied by the highest plasma sCD40L concentrations." (PMID 29780830, 2018). "Therefore, we hypothesize that CD40 may be expressed on EGCs and related to the intestinal barrier dysfunction during sepsis, because EGCs share many characteristics with astrocytes and are associated with intestinal epithelial cells." (PMID 36303116, 2022).